KIT (KIT proto-oncogene, receptor tyrosine kinase)
Diseases named in the same sentence as KIT in open-access papers (continued):
Sharing a sentence is not in itself a finding about the gene and the disease.
anaphylaxis (17 papers, 2013 to 2026). An acute hypersensitivity reaction that occurs from exposure to an allergen. "The observed high prevalence of the KIT p.D816V variant among individuals experiencing severe anaphylaxis has been described recently." (PMID 40397530, 2025). "Similar results were reported in a study in which 5% of the patients referred for severe anaphylaxis were found to have a clonal MC disease, with a KIT 816 mutation but a normal BST level." (PMID 39877259, 2025). "Nevertheless, screening for underlying cMCD (by peripheral blood KIT p.D816V variant detection using highly sensitive molecular methods) is indicated in all patients with severe anaphylaxis, especially HVA, to avoid unnecessary deaths." (PMID 38003556, 2023). "A KIT D816V mutation was present in 16 of the 20 patients with a CMCD with wasp venom anaphylaxis (80%) with an allele burden of 0.05% (0.01-1%)." (PMID 35281031, 2022). "Moreover, the KIT p.D816V variant and HαT are relevant in the context of predisposition to severe anaphylaxis; their detection requires specialised equipment and expertise, which limits their availability to specialised referral centers and increases associated costs." (PMID 40588688, 2025). "Recent studies have highlighted the importance of routine screening for the somatic missense KIT p.D816V variant in peripheral blood leukocytes (PBL), and its association with severe sting anaphylaxis." (PMID 40397530, 2025). "Given its relative scarcity among cell types other than MCs as well as its involvement in numerous debilitating MC-related disorders, KIT provides an alluring therapeutic target for anaphylaxis and MCAS." (PMID 36798116, 2023). "Mean BST values and mean KIT p.D816 V variant allele frequencies were significantly lower in patients with compared to those without a history of anaphylaxis." (PMID 40230786, 2025). "Furthermore, because the risk of venom-induced anaphylaxis is increased in patients with ISM with coexisting HaT, it is recommended to test for KIT D816V if the baseline tryptase is >8 ng/ml and to perform BM biopsy if positive." (PMID 39493747, 2024). "Regarding to the patients with CMCD without anaphylaxis, a KIT D816V mutation was present in 20 of the 24 patients with a CMCD without anaphylaxis (83%) with an allele burden of 0.06% (0.01-2.68%)." (PMID 35281031, 2022). "The presence of the KIT D816V mutation was found in 75% (N = 18) of patients with anaphylaxis, and 92% (N = 39) of patients without anaphylaxis (p = 0.042)." (PMID 34754417, 2021). "During anaphylaxis, DAO increased markedly in CMD (median 1142%), but only modestly in KIT p.D816V-negative patients (median 20%; p < 0.0001), independent of trigger or severity." (PMID 41612740, 2026). "For two patients with KIT D816V no data were obtained regarding neither symptoms of anaphylaxis nor allergy." (PMID 34754417, 2021). "To determine whether a KIT-specific ESO has any effect on the development and severity of anaphylaxis, here we assessed the impact that KitStop has using a well-established mouse model of passive systemic anaphylaxis, as well as compared its efficacy following varying routes of administration." (PMID 36798116, 2023). "Interestingly, the multiple reactor phenotype seems to oppose the BMM and HVA phenotype, that more frequently includes males, with no MCA‐associated symptoms other than anaphylaxis, low sBT and BMMC burden, in the absence of multilineage KIT mutation." (PMID 35344302, 2022).
chordoma (17 papers, 2009 to 2024). Chordomas are rare malignant tumors arising from embryonic remnants of the notochord in axial skeleton. "Among molecular targeted therapies, imatinib, an inhibitor of platelet-derived growth factor receptor-β and c-KIT, has been shown to be active in the treatment of advanced chordoma." (PMID 25018886, 2014). "One basket study looking at the efficacy of dasitinib; an inhibitor of PDGFR c-KIT, BCR-ABL, and ephrin receptor kinases; in chordoma found that the 6-month, 2-year, and 5-year overall survival for patients was 54%, 43%, and 18% respectively." (PMID 38881706, 2024). "Dasatinib, a small molecule inhibitor of the Src family of kinases, PDGFRα/β, and c-KIT, is currently the only TKI that has demonstrated activity against both chondrosarcoma (CS) and chordoma in a phase II clinical trial." (PMID 36430263, 2022). "Imatinib mesylate (IM), a specific tyrosine kinase inhibitor (TKI) targeting PDGFR and KIT, was the most frequently-used MTT in chordoma patients." (PMID 30775316, 2019). "A recent study reported that most chordomas express multiple RTKs, including PDGFR isoforms, EGFR, HER2, c-MET, and KIT." (PMID 27200287, 2016). "Following the immunohistochemical demonstration that PDGFR is activated in a majority of chordomas, patients with chordoma were treated with imatinib mesylate, a tyrosine kinase inhibitor active against PDGFR, BCR-ABL, and KIT." (PMID 26247786, 2015). "Successively, in a molecular/biochemical analyses of the three receptors targeted by IM (PDGFRB, PDGFRA, and KIT) in a series of 31 chordoma patients, it was proven that PDGFRB was highly expressed and phosphorilated whereas PDGFRA and KIT were less expressed but equally activated." (PMID 20109225, 2010).
gastric tumors (17 papers, 2006 to 2025). "And also, KIT/PDGFRA wild-type GISTs had significantly more primary gastric tumors and metastases to the lymph nodes than patients with KIT/PDGFRA-mutated GISTs, which commonly metastasized to the liver and peritoneum." (PMID 39447098, 2024). "Among the karyotypically abnormal GISTs of the present series, KIT exon 9 mutations (n = 10) were seen mostly in non-gastric tumors, the majority of which had complex karyotypes or were metastatic." (PMID 35284037, 2022). "Since no PDGFRA mutations were identified in non-gastric GISTs in this study, and to avoid any site-specific effect in KIT-mutated tumors, only gastric tumors were compared." (PMID 35284037, 2022). "Non-white participants were younger, on average (53.0 years vs. 59.0 years), and more likely to have stomach tumors (74% vs. 64%) and exon 11 KIT mutations (84% vs. 67%)." (PMID 23637977, 2013). "Finally, focusing on KIT-mutated GISTs, immunity-related terms were slightly more represented in intestinal tumors than gastric tumors." (PMID 33048845, 2020). "Moreover, KIT-mutated gastric GISTs featured an inferior degree of infiltration both when compared with PDGFRA-mutated gastric tumors and when compared with the KIT-mutated counterpart of the intestine." (PMID 33048845, 2020). "A trend for enrichment of immunity-related genes also emerged when contrasting PDGFRA versus KIT gastric tumors and overt GISTs versus miniGISTs." (PMID 33048845, 2020). "GISTs that occur in children are a separate clinicopathologic and molecular subset with predilection for girls, multifocal gastric tumors, and wild-type KIT/PDGFRA genotype." (PMID 25264210, 2014). "The gastric tumor demonstrated DOG1 and CD117 (KIT) positivity, with focal CD34 staining." (PMID 38538628, 2024).
squamous cell carcinoma (17 papers, 2012 to 2025). A carcinoma arising from squamous epithelial cells. "We recently reported one interesting case showing mutation-free c-KIT proto-oncogene overexpression and paradoxical hypermethylation in 54 cases of primary squamous cell carcinoma of uterine cervix (SCC)." (PMID 26607501, 2015). "Furthermore, in the same study, c-KIT expression was also associated with increased tumor size and distant metastasis, arguing that Sh-associated squamous cell carcinoma is more aggressive than Sh-unassociated squamous cell carcinoma." (PMID 39250522, 2024). "Immunohistochemical staining for CD5 and CD117 (KIT) is helpful in distinguishing them from squamous carcinomas originating in other organs, such as the lungs." (PMID 38201593, 2023). "In 54 cases of primary squamous cell carcinoma of uterine cervix (SCC) of uterine cervix, we recently demonstrated one case showing mutation-free, over-expression and paradoxical hypermethylation of the c-KIT proto-oncogene." (PMID 26607501, 2015). "We propose the hypothesis that increased methylation at the CpG islands might interfere with the binding of the CTCF repressor with the c-KIT promoter which regulates c-KIT proto-oncogene expression in c-KIT (+) squamous cell carcinoma of uterine cervix." (PMID 26607501, 2015). "In the same study, although the clinicopathologic features of tuft-like NEC and tuft-like squamous cell carcinoma (SQ) were different, both tumor types co-expressed BCL2 and KIT." (PMID 40406790, 2025).
allergies (16 papers, 2013 to 2025). "Most severe MCA events occur in combined forms of MCAS, where KIT-mutated MCs, IgE-dependent allergies and sometimes HAT are detected." (PMID 33261124, 2020). "We do not recommend the use of KIRA6 as an MC inhibitor in patients with allergies or other inflammatory diseases involving MCs, since the combined inhibitory activity against SFKs, KIT, and the ubiquitous UPR sensor IRE1α could cause detrimental side effects." (PMID 39676406, 2025). "Evaluating previous failed treatments with immunotherapy, 3 of 37 (8%) patients with KIT‐positive honeybee allergies had unsuccessful treatment." (PMID 40397530, 2025). "Given the crucial importance of mast cells in IgE-dependent and -independent allergic diseases, mast cell–targeting strategies, in particular selective KIT inhibition, are an attractive treatment approach for these disorders." (PMID 38764489, 2024). "The regulation of FcɛRI and KIT should be a promising strategy to control mast cell-mediated allergic reactions." (PMID 32023940, 2020). "Imatinib is known to inhibit KIT signal pathways, and the efficacy of this drug is shown in patients with severe refractory asthma, one of the mast cell-mediated allergic diseases." (PMID 32023940, 2020). "Although KIT inhibitors have the advantages of immediate, complete, sustained and non-toxic remission in anti-allergy, this new drug indication warrants further studies in patients with allergic diseases." (PMID 39148726, 2024). "For example, in patients with a high mass of neoplastic MC, advanced SM, and severe IgE-dependent allergies, combined therapy with a KIT-targeting drug or cladribine and omalizumab may be required to bring MCAS events under control." (PMID 33261124, 2020). "Mast cells are involved in allergic reactions via their KIT-mediated and FcɛRI-mediated responses." (PMID 32023940, 2020). "Thus, targeting KIT signaling may show promise for the treatment of allergic diseases involving mast cells." (PMID 38764489, 2024). "Interference with the KIT-mediated and FcεRI-mediated signal pathways has been proposed as a potential strategy to control mast cell-mediated allergic reactions, highlighting the importance of KIR2DL4 as a target for allergic diseases." (PMID 32023940, 2020).
uveal melanoma (16 papers, 2012 to 2025). A melanoma derived from melanocytes of the uveal tract. "For instance, in metastatic melanoma, activation of c-KIT causes apoptosis, while activation in uveal melanoma results in increased proliferation." (PMID 33807778, 2021). "Nonetheless, most primary uveal melanomas express KIT protein on tumor immunohistochemical analysis, making KIT a potential target for treatment." (PMID 37239381, 2023). "In a study investigating c-KIT-positive metastatic uveal melanoma (UM), increased imatinib resistance was observed in cells incubated with either SCF-supplemented medium or microvascular endothelial cells-conditioned medium." (PMID 33807778, 2021). "Mutations in BRAF, KIT and NRAS are rarely seen in uveal melanoma; however more than 80 percent of uveal melanomas have mutations in GNAQ or GNA11." (PMID 26334521, 2015). "In regard to target therapies, BRAF and KIT inhibitors are not included among treatment options, as uveal melanomas usually lack BRAF and KIT mutations." (PMID 34680428, 2021). "A clinical study also found that there was no clinical efficacy of imatinib in uveal melanomas expressing SCF/KIT without mutations." (PMID 23420128, 2013). "Specifically, in uveal melanoma, KITLG-dependent stimulation facilitates the proliferation and transformation of uveal melanoma cells via SCF/c-KIT autocrine loop activation." (PMID 38213737, 2024). "For instance, imatinib, which targets BCR-ABL, c-Abl, PDGFR and c-Kit, was found not be effective in uveal melanoma despite high expression of KIT, an unexpected finding that was interpreted to be related to the lack of ERK phosphorylation in these tumors." (PMID 34888523, 2021).
vulvar melanoma (16 papers, 2014 to 2025). A usually pigmented, nodular or polypoid malignant neoplasm that originates from melanocytes and arises from the vulva. "In a case of metastatic vulvar melanoma harboring an exon 17 KIT mutation, avapritinib produced a favorable CNS response despite prior treatment failure and high tumor burden." (PMID 41301010, 2025). "It has been reported that significant proportion of acral, mucosal and vulvar melanomas have KIT mutations." (PMID 36720768, 2023). "What is interesting is that the KIT mutation rate was higher in vulvar melanoma (31.4%) than in vaginal melanoma (6.2%)." (PMID 36291906, 2022). "The KIT gene mutation, which rarely appears in cutaneous melanoma patients, appears to be commonly occurring in vulvar melanoma (from 22 up to 31% of cases)." (PMID 36291906, 2022). "Genitourinary tract and anorectal melanomas (both in males and females) frequently show KIT mutations and amplifications, together with NRAS mutations; notably, KIT mutations are uncommon in vaginal melanomas but are frequently present in vulvar melanomas." (PMID 35008570, 2021). "KIT mutation has been reported to be a marker of better progression-free survival in vulvar melanomas." (PMID 34571863, 2021). "In our study, 5 out of 71 (7.0%) samples had a KIT mutation; 2 mutations in tumors of the head and neck region and 2 in vulvar melanomas." (PMID 28380455, 2017). "In our study, 2 out of 9 (22.2%) vulvar melanomas had a KIT mutation." (PMID 28380455, 2017). "They found that 35% (8 out of 23) of vulvar melanomas harbored KIT mutations." (PMID 28380455, 2017). "Activating c-KIT mutations have been found in patients with vulvar melanoma." (PMID 24535703, 2014). "Notably, c-KIT mutations are present in more than 20% of vulvar melanomas, suggesting that tyrosine kinase inhibitors could be a viable option for recurrent disease." (PMID 39797152, 2024). "However, our findings are different from those of Hou and colleagues that showed that vulvar melanoma may be associated with a much higher KIT mutation rate than vaginal melanoma." (PMID 34102999, 2021). "In our cohort, we also found an increased c-KIT protein expression in approximately half of the patients, suggesting a role of c-KIT in vulvar melanoma." (PMID 24535703, 2014). "In another study evaluating 65 vulvovaginal cases, the KIT mutations were found in 18% of vulvar melanomas, but none in vaginal tumors." (PMID 34065883, 2021). "The other response was observed in the patient with KIT-mutated vulvar melanoma lacking a BRAF mutation." (PMID 28428884, 2017). "The prognostic predictors reported in the literature are not unequivocal and the role of lichen sclerosus and c-KIT mutations in the aetiology of vulvar melanoma is unclear." (PMID 24535703, 2014). "Thus, we performed a) a comprehensive literature review, b) a clinicopathological review of 33 vulvar melanoma cases of an Australian cohort to identify potential histopathological predictors of outcome, and c) immunohistochemistry for c-KIT expression in a respective tissue microarray." (PMID 24535703, 2014).
myeloid sarcoma (15 papers, 2014 to 2025). A tumor mass composed of myeloblasts or immature myeloid cells. "This case also demonstrates mutation of c-KIT (exon 17), which is seen affecting 15 % of the myeloid sarcoma cases." (PMID 40570478, 2025).
smooth muscle tumor (15 papers, 2011 to 2026). A benign or malignant myomatous neoplasm arising from smooth muscle. "In a large kindred of 22 members with the c-KIT mutation, the index patient had esophageal thickening and was diagnosed with multiple smooth muscle tumors, dying within the 2 months follow-up." (PMID 34064058, 2021). "GISTs were difficult to diagnose and treat previously; however, now, they are diagnosed and differentiated from smooth muscle tumors with the help of immunohistochemistry, KIT, and CD34 positivity." (PMID 41497126, 2026). "GISTs were considered smooth muscle tumors based on their histological characteristics until the identification of KIT (CD117) expression and c-KIT mutations." (PMID 40417261, 2025). "The discovery of CD34 expression (80-90%) and the receptor tyrosine kinase KIT (CD117) in many GISTs suggested that they were a specific entity distinct from smooth muscle tumours." (PMID 25069607, 2014). "Most GISTs stain for KIT protein (CD117; 95%) and anoctamin-1 (DOG-1; 98%), but most do not stain for desmin, a biomarker of smooth muscle tumors." (PMID 32264886, 2020).
triple-negative breast carcinoma (15 papers, 2012 to 2025). An invasive breast carcinoma which is negative for expression of estrogen receptor (ER), progesterone receptor (PR), and human epidermal growth factor receptor 2 (HER2). "Proteomics, phosphoproteomics and kinome analysis as well as several kinase activity assessment assays established the importance of diminution JNK activity and c-KIT-AKT-mTOR axis enhancement in the establishment of RH1 resistance in the triple-negative breast cancer cells." (PMID 31336714, 2019). "Protein expression and gene copy number of c-KIT, VEGFR2 and PDGFRα in relation to triple-negative breast cancer (TNBC)." (PMID 25025175, 2014). "Furthermore, there has been recent interest in two candidate genes in this region, with increased gene copy number for genes KIT and VEGFR2 found in triple negative breast cancer, an aggressive and difficult to treat form of the disease." (PMID 23190577, 2012).
embryonal carcinoma (14 papers, 2007 to 2026). A non-seminomatous malignant germ cell tumor characterized by the presence of large germ cells with abundant cytoplasm resembling epithelial cells, geographic necrosis, high mitotic activity, and pseudoglandular and pseudopapillary structures formation. "The immunohistochemical markers in current use include CD117/KIT, POU5F1 (OCT3/4), PLAP, and CT45 (germinoma); AFP, SALL4 and glypican 3 [yolk sac tumour (YST)]; CD30 (embryonal carcinoma); and HCG (choriocarcinoma)." (PMID 23861728, 2013). "Based on our results, we suggest that KIT, TNFRSF8, and ERBB4 may be suitable targets for the treatment of germinoma, embryonal carcinomas, and yolk sac tumors, respectively." (PMID 32999426, 2020).